TUSC7 (tumor suppressor candidate 7)
Diseases named in the same sentence as TUSC7 in open-access papers (continued):
Sharing a sentence is not in itself a finding about the gene and the disease.
dermatitis (1 paper, 2017). An inflammatory process affecting the skin. "We demonstrated that TUSC7 rs1829346 and rs36080650 were significantly associated with dermatitis." (PMID 28814798, 2017). "The variation in the rs1829346 sequence may create a new binding site for miR-1304, inhibiting the expression of TUSC7, regulating cell proliferation proteins and ultimately leading to a higher risk of CRT-induced dermatitis." (PMID 28814798, 2017).
tumor (38 papers, 2014 to 2026). "Lower TUSC7 expression levels in NSCLC tissues were associated with larger tumor sizes and higher TNM stages." (PMID 27685633, 2016). "TUSC7 expression in HCC tissues was negatively associated with more tumor nodes, more venous infiltration, advanced Edmondson-Steiner grading, and advanced TNM tumor stage." (PMID 27002617, 2016). "TUSC7 overexpression could suppress tumor cell proliferation, invasion, migration and colony formation, suggesting that TUSC7 might be a prognostic and diagnostic biomarker as well as therapeutic target." (PMID 31652435, 2019). "In addition, patients with lower TUSC7 levels had poorer overall survival, and there were significant associations between TUSC7 levels with tumor size and pathological staging." (PMID 29530057, 2018). "Moreover, we also found that down-regulation of TUSC7 associated with distant metastasis (OR = 2.85, 95% CI: 1.46–5.55, P = 0.002) and larger tumor size (OR = 0.41, 95% CI: 0.23–0.72, P = 0.002)." (PMID 28938655, 2017). "Moreover, the underlying mechanism of TUSC-7 as a potential tumor suppressor is elusive." (PMID 31652435, 2019). "Consequently, decreased TUSC7 expression associated with a worse survival in tumor patients." (PMID 28938655, 2017). "Together, these findings position TUSC7 as a promising biomarker for tumor detection and a potential candidate for therapeutic stratification." (PMID 41964023, 2026). "Higher TNM stage and greater tumor size have been correlated to lower Tumor suppressor candidate 7 (TUSC7) expression in NSCLC tissues." (PMID 39912974, 2025). "A typical example is TUSC7 (Tumor Suppressor Candidate 7), which has low expression in multiple tumor types, and restoring the expression of TUSC7 can significantly inhibit the proliferation and metastasis of tumor cells." (PMID 40621472, 2025). "According to earlier studies, TUSC7 can serve as a tumor suppressor gene in several tumors via inhibiting the expression of such miRNAs as miR-10a, miR-211 and miR-23b." (PMID 38054829, 2023). "In vivo study confirmed the effective inhibition of TUSC7 exhibited on tumor growth, and the Notch signaling inactivation by using FLI-06 also suppressed the in vivo tumor expansion, further proved its suppressive functions." (PMID 34656164, 2021). "Our final panel consisted of seven up‐regulated DElncRNAs (CCAT1, CCAT2, H19, HOTAIR, HULC, MALAT1, PCAT1), which were also known as oncolncRNAs and three down‐regulated lncRNAs (MEG3, PTENP1, and TUSC7) as tumor suppressor lncRNAs (tslncRNAs)." (PMID 33094859, 2021). "It was previously shown that TUSC7 low-expression is related to poor prognosis, and increases the proliferation rate of tumor cells." (PMID 31652435, 2019). "Low TUSC7 also decreased overall survival of patients with EC, and overexpression of TUSC7 inhibited colony formation in vitro and tumor volume and weight in vivo." (PMID 29530057, 2018). "The tumor suppressor candidate 7 (TUSC7) is an antisense lncRNA: if downregulated, it acts as a possible tumor suppressor in several cancers." (PMID 29596364, 2018). "In other words, cancer patients with low TUSC7 expression in tumor tissues were more prone to develop DM." (PMID 28938655, 2017). "The results indicated that decreased TUSC7 expression was significantly related to unfavorable clinical prognosis in patients with various tumor types." (PMID 28938655, 2017). "Thirdly, the aggregated results showed that decreased TUSC7 expression was positively correlated with distant metastasis and larger tumor size." (PMID 28938655, 2017). "TUSC7 was a newly identified ncRNA gene, reported to be decreased expression in various cancer cells and tumor tissues as a tumor suppressor." (PMID 28938655, 2017).
tumor (continued). "While Tusc7 seems to act as a tumor suppressor and is reduced in severaltypes of cancer, the picture for taurine up-regulated 1 (Tug1), another p53regulated lncRNA, is not as clear." (PMID 27508057, 2016). "Our results showed that TUSC7 levels were significantly decreased in HCC tissues compared with adjacent non-tumor tissues (p < 0.05)." (PMID 27002617, 2016). "TUSC7 acts as a tumor suppressor in human cancers by interacting with miRNAs, such as miR-23b and miR-211." (PMID 27002617, 2016). "In gastric cancer, Tusc7 expression is reduced in patient samples, and incell lines decreases tumor cell growth." (PMID 27508057, 2016). "Further analysis showed that the expression level of TUSC7 was significantly correlated with tumor nodes (p < 0.001), venous infiltration (p = 0.017), Edmondson-Steiner grading (p = 0.003), and tumor-node-metastasis (TNM) tumor stage (p = 0.004)." (PMID 27002617, 2016). "The authors also assessed the correlation between TUSC7 expression and clinicopathological data in CRC patients, and found that low expression of TUSC7 was correlated with larger tumor size, higher tumor stage, and more distant metastasis." (PMID 27148353, 2016). "Based on these findings, we hypothesized that TUSC7 acts as a tumor suppressor by interacting with miRNAs in CLL cells." (PMID 40056063, 2025). "Moreover, TUSC7 functions as a tumor suppressor by inhibiting cell proliferation and promoting apoptosis in CLL." (PMID 40056063, 2025). "The underlying role of long non-coding ribonucleic acids (lncRNAs) in malignancies has attracted much attention, among which tumor suppressor candidate 7 (TUSC7) is a novel tumor suppressor gene whose regulatory mechanism in human cerebral gliomas remains inconclusive." (PMID 37100464, 2023). "And increasing the expression of TUSC7 suppressed tumor growth." (PMID 34375306, 2021). "In vitro experiments demonstrated that overexpression of TUSC7/inhibition of miR-224 repressed cell proliferation and chemotherapy resistance via DESC1/EGFR/AKT pathway, and in vivo experiments demonstrated that overexpression of TUSC7 decreased tumor growth and chemotherapy resistance." (PMID 29530057, 2018). "Finally, in vivo experiments demonstrated that overexpression of TUSC7 decreased tumor growth and chemotherapy resistance." (PMID 29530057, 2018). "We observed that overexpression of TUSC7 inhibited tumor volume, size and weight." (PMID 29530057, 2018). "And overexpression of TUSC7 further decreased tumor volume and weight in cisplatin-treated mice." (PMID 29530057, 2018). "For instance, inhibition of tumor suppressor lncRNA TUSC7 (tumor suppressor candidate 7, TUSC7) could promote OS cell proliferation and enhance colony formation in vitro." (PMID 28103585, 2017). "We hypothesize that TUSC7 may function as a potential tumor suppressor in CLL." (PMID 40056063, 2025). "Furthermore, the mechanism of TUSC7 as a potential tumor suppressor remains elusive." (PMID 37100464, 2023). "Moreover, we also observed overexpression of TUSC7 inhibited tumor volume and weight." (PMID 29530057, 2018). "Furthermore, decreased TUSC7 expression is also related to tumor clinical characteristics." (PMID 28938655, 2017).
tumor (continued). "In summary, our data indicate that TUSC7 may function as a tumor suppressor in HCC." (PMID 27002617, 2016). "Growing evidence indicates that lncRNAs can also function as tumor suppressor genes, such as TUSC7 (Tumor Suppressor Candidate 7) and LOC285194." (PMID 32731343, 2020). "Firstly, we respectively analyzed the correlation of expression levels of TUSC7 and E-cadherin as well as TUSC7 and vimentin in 75 paired HCC tissues and adjacent non-tumor tissues by immunohistochemical staining." (PMID 27002617, 2016). "First, we examined the lncRNA TUSC7 expression level in 75 paired HCC tissues and adjacent non-tumor tissues by qRT-PCR and normalized them to GAPDH." (PMID 27002617, 2016). "Differential expression analysis revealed significant divergence in lncRNA profile between parental tumors and tumor-derived cell cultures in vitro, including the following particles: MALAT1, CASC2, H19, TUSC7, XIST, RP11-838N2.4, DLX6-AS1, GLIDR, MIR210HG, SOX2-OT." (PMID 33245508, 2022). "Furthermore, we tested the action of TUSC7 on tumor invasion and metastasis of HCC cells by taking different approaches and found that TUSC7 inhibited cell invasion and metastasis in HCC." (PMID 27002617, 2016). "Silencing TUSC7 significantly promoted tumor growth in vivo in treated mice compared with negative-control mice." (PMID 27685633, 2016). "Significant overexpression of LPAR3 has been identified in HCC tumor margins and was interestingly overexpressed in the CCA portion of combined HCC-CCA, potentially owing to the increased aggressiveness along with NEFL and TUSC7 that were also overexpressed in the CCA portions." (PMID 40424447, 2025). "Furthermore, TUSC7 levels were notably lower in tumor tissues arising from patients with tumor recurrence than that without tumor recurrence (p < 0.001)." (PMID 27002617, 2016). "In addition, in our independent cohort, TUSC7 expression was significantly downregulated in tumor samples compared with matched adjacent non-tumoral tissue, a pattern that was independently validated using transcriptomic data from the Clinical Proteomic Tumor Analysis Consortium (CPTAC)." (PMID 41964023, 2026).
cancer (15 papers, 2014 to 2025). A tumor composed of atypical neoplastic, often pleomorphic cells that invade other tissues. "In conclusion, our meta-analysis offers evidence that low TUSC7 expression is a risk factor for distant metastasis in diverse cancers." (PMID 28938655, 2017). "It aimed to more precisely evaluate the association between TUSC7 expression and clinical consequence of human cancer." (PMID 28938655, 2017). "We carried out current systematic review and meta-analysis to explore the decreased expression of TUSC7 associate with prognostic and clinicopathological characteristic in cancer patients." (PMID 28938655, 2017). "We mainly discussed the expression of TUSC7 associate with prognosis, metastasis and clinicopathological characteristics of cancer patients." (PMID 28938655, 2017). "Competitive endogenous binding between TUSC7 and onco-miRNAs has been frequently reported as associated with cancer-related processes." (PMID 29147648, 2017). "Functionally, the sponge type of TUSC7 regulation of miR-146a inhibited Notch signaling functions, and affected the cancer progression and stem cells’ renewal in Erlotinib resistant PC9 cells (PC9ER) and Erlotinib resistant HCC827 cells (HCC827ER) cells." (PMID 34656164, 2021). "To further identify the candidates to improve the TKIs treatments sensitization, we tentatively explored the supporting role of TUSC7 in cancer suppression, trying to establish the m6A correlated lncRNA functions in modulating the TKIs therapies resistance." (PMID 34656164, 2021). "Although TUSC7 was found to be significantly correlated with the prognosis of cancer patients, some limitations should be concerned for explaining the results of this meta-analysis." (PMID 28938655, 2017). "Our meta-analysis demonstrated that cancers patients detected with low TUSC7 expression were more prone to develop distant metastasis." (PMID 28938655, 2017). "Here we implemented present meta-analysis to evaluate the relationship of TUSC7 expression levels with prognosis results and clinicopathological parameter in cancer patients." (PMID 28938655, 2017). "Previous studies have suggested the ceRNA mechanism of TUSC7 in various cancers." (PMID 40056063, 2025). "Previous studies have demonstrated that lncRNA TUSC7 exerts inhibitory effects in various cancers." (PMID 40056063, 2025). "In LUAD, YTHDF2-mediated inhibition of lncRNA TUSC7 provokes the resistance to erlotinib, as TUSC7 could sponge miR-146a and inhibit Notch signaling to decrease the cancer progression and improve sensitivity to erlotinib." (PMID 36810281, 2023). "Recent studies show that TUSC7 may function as a competing endogenous RNA (ceRNA) or a molecular sponge by modulating the biological functions and concentration of miRNAs in cancers." (PMID 27002617, 2016). "Accordingly, TUSC7 was identified as a robust suppressor of cancer." (PMID 27002617, 2016). "In patient samples, Tusc7 was shown to be reduced in cancer compared tonormal colon tissue." (PMID 27508057, 2016). "Therefore, further explore the relationship between TUSC7 and cancer is absolutely necessary." (PMID 28938655, 2017). "Bench study showed that, TUSC7 sponged to miR-146 and then released NUMB to control Notch signaling, the latter of which was critical for maintaining cancer stem cells (CSCs) pool." (PMID 34656164, 2021).
adenocarcinoma (1 paper, 2021). A common cancer characterized by the presence of malignant glandular cells. "The highly expressed TUSC7 indicated better progression-free estimates in adenocarcinoma, comparing to the lower expressed groups." (PMID 34656164, 2021).
TUSC7 also shares sentences with these, for which no sentence is quoted: endometrial carcinoma (3 papers); non-small cell lung carcinoma (3); pancreatic ductal adenocarcinoma (2); anaemia (1); atherosclerosis (1); cardiovascular disorder (1); liver cancer (1); lung adenocarcinoma (1); myelosuppression (1); ovarian carcinoma (1); Phelan-McDermid syndrome (1).